CCN1 (cellular communication network factor 1)
Diseases named in the same sentence as CCN1 in open-access papers (continued):
Sharing a sentence is not in itself a finding about the gene and the disease.
breast cancer (continued). "Immunofluorescence analysis of CCN1 protein revealed that, in addition to its cytoplasmic location, CCN1 exhibited an apparent nuclear-staining pattern in the majority of MCF-7 breast cancer cell lines, with no evident differences between wild-type and mutant CCN1." (PMID 35148282, 2022). "However, an opposite pattern was identified for other of them (VEGFR2/KDR, CYR61/CCN1, IGFBP1, IGFBP4, IGFP6) and no changes for CTGF/CCN2, and IGFP6 across the breast cancer subtypes." (PMID 33531624, 2021). "Indeed, CCN1 overexpression was sufficient to increase steady-state FASN protein to levels similar to those found in SKBR3 cells (data not shown), a naturally occurring FASNoverexpressing breast cancer cell line." (PMID 27713913, 2016).
melanoma (42 papers, 2007 to 2026). A malignant, usually aggressive tumor composed of atypical, neoplastic melanocytes. "Melanoma progression is associated with several molecular changes including CCN1/CYR61, MCAM/MUC18 and PAR-1." (PMID 20805990, 2010). "In an animal model, loss of CCN1 from CAFs impaired metastasis of melanoma cells, neovascularization, and collagen deposition, emphasizing that CAFs coordinate cellular behavior in a tumor microenvironment and that CCN1 may be a novel target." (PMID 38363129, 2024). "In this article, we use a syngeneic model of melanoma metastasis to begin to probe the role of the proangiogenic matricellular protein CCN1 in melanoma." (PMID 38363129, 2024). "Using melanoma bulk tumor RNA-seq data, we determined that CCN1 expression correlated with stromal gene expression scores." (PMID 38363129, 2024). "Analysis of single-cell expression data revealed that, in patients with melanoma, CCN1 was the most highly expressed in CAFs, but was also found in endothelial cells and malignant cancer cells." (PMID 38363129, 2024). "We examined the requirement of CCN1 in the endothelium for the highly metastatic B16F10 melanoma model to adhere to blood vessels in vivo." (PMID 28694244, 2017). "CCN1 has been identified as the direct target gene of cAMP-response element-binding protein (CREB) in melanoma, and its expression is negatively regulated by the CREB-mediated inhibition of CCN1 promoter transcription." (PMID 22481923, 2012). "Note that CCN1 was still expressed normally in melanoma cells." (PMID 38363129, 2024). "As drug resistance is linked to matrix deposition and neoangiogenesis, these data suggest that CCN1, due to its multifaceted role, may represent a novel therapeutic target for drug-resistant melanoma." (PMID 38363129, 2024). "To examine the role of Col1A2-Cre-CAF–specific Ccn1 expression in melanoma metastasis, we used mice expressing a tamoxifen-dependent Cre recombinase expressed under the control of a fibroblast-specific promoter/enhancer that was derived from the human COL1A2 gene." (PMID 38363129, 2024). "Indeed, our conclusion that CCN1 is a novel therapeutic target in melanoma is supported by several lines of patient-derived and animal model-derived data." (PMID 38363129, 2024). "Although it promotes colorectal cancer, pancreatic, ovarian, and breast cancer, the role of CCN1 in patients with melanoma remains unclear." (PMID 38363129, 2024). "CCN1 knockdowns resulted in decreased adhesion of cancer cells to the EC monolayer in stiff matrices, while in vivo CCN1 knockouts in a highly metastatic mouse melanoma model also revealed decreased cancer cell adhesion to blood vessels and reduced metastasis." (PMID 35806421, 2022). "Additionally, HIF-1α binds to AP-1-binding motif within Cyr61 (also called CCN1) promoter and induces Cyr61 expression, which plays a prometastatic role in human melanoma cells under hypoxia." (PMID 34956899, 2021). "Our data provide new and valuable insights into how fibroblast-specific expression of a matricellular protein coordinates activity among multiple cell types in the tumor microenvironment and suggest that CCN1 may represent a novel therapeutic target for drug-resistant melanoma metastasis." (PMID 38363129, 2024). "Finally, we identify the importance of Col1A2-Cre-fibroblast (i.e., universal fibroblast) expression of Ccn1 in coordinating these activities, emphasizing the importance of the CAF in the phenotype and development of cancers, including melanoma." (PMID 38363129, 2024). "Additionally, CREB negatively regulates both activating protein-2 (AP-2) and cellular communication network factor 1 (CCN1/CYR61), promoting cell growth and tumor angiogenesis in A375SM and C8161-c9 high metastatic melanoma cells." (PMID 33126560, 2020).
melanoma (continued). "Interestingly, TNF-α signalling via the NF-κB pathway was significantly downregulated with a reduction ranging from 7- to 40-fold in expression of some of its prooncogenic target genes (e.g., JUNB, FOS, DUSP1) and melanoma-related genes (e.g., EGR3, NR4A3, CCN1)." (PMID 34497073, 2021).
pancreatic cancer (42 papers, 2007 to 2025). "We found that Ccn1‐deficient pancreatic cancer cells exhibit reduced expression of collagens, including Col4a1, Col4a2, Col5a1, Col6a1, Col6a2, Col6a3, and Col8a1." (PMID 40287974, 2025). "Upon overexpression of Col5a1 in Ccn1‐deficient pancreatic cancer cells, the expression of Cxcl1 and Cxcl5 were upregulated." (PMID 40287974, 2025). "At the transcript level, mRNA expression of Ccl2, Ccl7, Cxcl1, Cxcl3, and Csf2 was markedly downregulated in Ccn1‐deficient pancreatic tumors, whereas Cxcl5, Csf1, and Csf3 expression remained unchanged, and Ccl20 mRNA was elevated." (PMID 40287974, 2025). "Pathologic tumor neovascularization and aggressiveness have been linked to the expression of Cyr61/CCN1 in breast and pancreatic cancer cells." (PMID 33142239, 2020). "Moreover, Ccn1‐deficient pancreatic cancer cells exhibit elevated sensitivity to gemcitabine, with minimal activation of reactive oxygen species (ROS) level following treatment." (PMID 40287974, 2025). "Notably, combination therapy with gemcitabine and anti‐PD1 antibody yields enhanced efficacy in Ccn1‐deficient pancreatic cancer." (PMID 40287974, 2025). "Similarly, mRNA levels of Col5a1, Col6a1, Col6a2, Col6a3, and Col8a1 were significantly reduced in Ccn1‐deficient pancreatic tumors, while Col4a1 and Col4a2 were unaffected." (PMID 40287974, 2025). "CCN1 modulates the tumor microenvironment in pancreatic cancer by promoting collagen‐dependent chemokine production, thereby facilitating immune evasion." (PMID 40287974, 2025). "In our study, we observed that deletion of Ccn1 in pancreatic cancer cells results in enhanced infiltration of immune cells and suppression of tumor growth." (PMID 40287974, 2025). "Ccn1 depletion in pancreatic cancer cells promotes macrophage invasion and polarization towards the M1 phenotype." (PMID 40287974, 2025). "The key role of CCN1 glycoprotein in regulating desmoplasia in pancreatic cancer has been previously proven by us." (PMID 41035776, 2025). "To investigate the functions of CCN1 in pancreatic cancer, we knocked out CCN1 in Panc1 cells using transient plasmid-based CRISPR-Cas9 technology." (PMID 39273316, 2024). "Here, we used the same model to study the direct communication between pancreatic cancer cells and PSCs, with a focus on the function and regulation of CCN1." (PMID 39273316, 2024). "Increased expression levels of CCN1 have been reported in pancreatic cancer and its metastatic lesions." (PMID 39273316, 2024). "To this end we knocked out CCN1 in the pancreatic cancer cell line Panc1 via the CRISPR-Cas9 technique." (PMID 39273316, 2024). "Our data are consistent with recent observations linking CCN1 expression to drug resistance in pancreatic cancers." (PMID 38363129, 2024). "The MAZ transcription factor is a downstream target of the oncoprotein Cyr61/CCN1 and promotes pancreatic cancer cell invasion via CRAF-ERK signaling." (PMID 38111008, 2023). "Other studies showed that the Akt/NF-κB signaling pathway was promoted by CCN1 and miRNA-23b-3p and involved in the tumorigenicity of pancreatic cancer." (PMID 35600049, 2022). "A previous study indicated that CCN1 promotes tumorigenicity by activating the AKT/NF-κB pathway in pancreatic cancer." (PMID 35785168, 2022). "MAZ, which is a downstream molecular of the Cyr61/CCN1, promotes pancreatic cancer cell invasion via CRAF-ERK signaling." (PMID 34183010, 2021). "Hh signaling is also associated with cellular communication network factor 1 (CCN1), Notch1, Vasohibin 2 (VASH2), and Ski in pancreatic cancer." (PMID 34440799, 2021). "The MAZ, which is a downstream gene of the oncoprotein Cyr61/CCN1, promotes pancreatic cancer cell migration and invasion via CRAF-ERK signaling." (PMID 34183010, 2021). "Cyr61/CCN1 is also expressed in pancreatic cancer and in human chondrosarcoma cells where it appears to up-regulate MMP13 expression and cell migration." (PMID 23977121, 2013).
pancreatic cancer (continued). "Notably, Ccn1 deletion enhances the efficacy of immunotherapy, effectively inhibiting pancreatic tumor growth." (PMID 40287974, 2025). "We therefore hypothesized that TGF-β1 and LPA might also be involved in the regulation of CCN1 expression in pancreatic cancer cells." (PMID 39273316, 2024). "In light of our results and those of others, conclusions about the exact roles of CCN1 in pancreatic cancer cells need further studies as other effectors might be involved too, which lead to seemingly contradicting results." (PMID 39273316, 2024). "For example, CCN1/Cyr61 secreted by pancreatic cancer cells may promote migration of endothelial cells." (PMID 33869254, 2021). "Moreover, our results imply a miRNA-based mechanism for the regulation of aggressive behaviors of pancreatic cancer cells by Cyr61/CCN1." (PMID 21232118, 2011). "Cyr61/CCN1 expression was also detected in different pancreatic cancer cell lines." (PMID 21232118, 2011). "To further elucidate the role of CCN1 in PDAC progression, we generated Ccn1 knockout in mouse pancreatic cancer cells KPC and Pan02." (PMID 40287974, 2025). "Our findings elucidate the unrecognized role of Ccn1 in the TME and its mechanisms in regulating both immune cells and pancreatic cancer cells." (PMID 40287974, 2025). "MAZ transcription factor was the downstream target of the oncoprotein Cyr61/CCN1, which promoted the invasion of pancreatic cancer cells through the CRAF-ERK signal." (PMID 36890610, 2023). "MAZ is a downstream molecule of Cyr61/CCN1, which expands the invasion of pancreatic cancer cells through CRAF-ERK signaling." (PMID 36890610, 2023). "A previous study confirmed that CCN1 positively regulates tumour growth and helps cells resist apoptosis via activating the AKT/NF-κB signalling pathway in pancreatic cancer." (PMID 35785168, 2022). "Further, pancreatic cancer cells lacking Ccn1 are sensitive to TNFα‐induced cell death and show inhibited polarization from M1 to M2 macrophages." (PMID 40287974, 2025). "Additionally, the analysis of the publicly available microarray dataset GSE71729 confirmed a positive correlation between CCN1 and ENPP2, as well as TGFB1 expression in pancreatic cancer patients." (PMID 39273316, 2024). "Interestingly CCN1 is detected in the early precursor lesions, and intensifies with disease progression in PDAC and has supporting activity in pancreatic cancer growth, invasiveness, and drug resistance." (PMID 32294968, 2020). "CCN1 induces EMT and stem cell-like traits in pancreatic cancer." (PMID 29088803, 2017). "To further validate whether Ccn1 deletion can enhances the efficacy of anti‐PD1 and gemcitabine in pancreatic cancer treatment, we established an orthotopic pancreatic tumor model in mice by inoculating KPC cells, followed by treatment with anti‐PD1 and gemcitabine." (PMID 40287974, 2025).
osteosarcoma (41 papers, 2012 to 2025). A usually aggressive malignant bone-forming mesenchymal neoplasm, predominantly affecting adolescents and young adults. "Cyr61/CCN1 has been linked to both skeletal (osteosarcoma) and prostate cancer." (PMID 23977121, 2013). "Further, inhibition of CYR61/CCN1 in a mouse osteosarcoma metastasis model led to reduced tumor vasculature, decreased metastasis to the lung, and the finding that microvessel density potentially correlated with risk of metastasis." (PMID 40374715, 2025). "We established that the expression level of Cysteine-rich protein 61 (CYR61/CCN1) correlates to tumor neo-vascularization and dissemination in preclinical and clinical osteosarcoma samples." (PMID 40038783, 2025). "We previously demonstrated that Cysteine-rich protein 61 (CYR61/CCN1) expression level is correlated to osteosarcoma aggressiveness in preclinical model and in patient tumor samples." (PMID 30642298, 2019). "The CCN1 expression level in osteosarcoma biopsies has been shown to correlate with poor prognosis, regardless of metastatic or nonmetastatic disease." (PMID 24551846, 2014). "CCN1 is located on chromosome 1 that often undergoes gain or amplification in osteosarcoma." (PMID 40442778, 2025). "Furthermore, a study in osteosarcoma tumours determined that silencing CCN1 reduces tumour vascularisation and slows the growth of osteosarcoma cells resulting in a reduction in subsequent lung metastases." (PMID 35052688, 2021). "Moreover, CCN1 also plays a central role in metastatic osteosarcoma by upregulating Twist expression." (PMID 29088803, 2017). "Moreover, an in vivo murine model showed that overexpression of CCN1 in the low-metastatic human SaOS-2 osteosarcoma cell line increased cell proliferation and promoted lung metastasis." (PMID 24551846, 2014). "We showed previously that statins induce anti-tumor effects on osteosarcoma cells, and lead to the down-regulation of cysteine rich protein 61 (CYR61/CCN1) expression level in these tumor cells." (PMID 40038783, 2025). "CCN1, CCN2, CCN3 and CCN4 are all poorly expressed in healthy adult bony tissues, but they are up regulated in primary samples as well as osteosarcoma cell lines." (PMID 34228239, 2021). "CCN1 expression is higher in osteosarcoma tumours compared to normal bone tissue and further increased in metastatic tissues." (PMID 40442778, 2025). "CCN4 also showed similar correlation like CCN1 and CCN3 in osteosarcoma." (PMID 24551846, 2014). "CCN1 induces MMP-2, MMP-9, MMP-14 and TIMP-3, mediates prometastatic effects via the IGF-1/IGF1Rβ pathway, and is elevated in MG63 M7 and M10 sublines selected in vivo for a migratory phenotype; in addition, its inhibition decreases lung-metastatic potential of osteosarcoma cell lines in vivo." (PMID 34228239, 2021). "CCN1 and CCN2 do not promote osteosarcoma cell proliferation per se but protect cells from apoptosis and decrease chemotherapeutic efficacy." (PMID 34228239, 2021).
glioma (33 papers, 2012 to 2025). A benign or malignant brain and spinal cord tumor that arises from glial cells (astrocytes, oligodendrocytes, ependymal cells). "CCN1 has been reported to be overexpressed in 48 to 69% of primary gliomas and is associated with PFS and OS." (PMID 35204054, 2022). "As for CCN1, glioma‐related research had primarily focused on its immunomodulation effect of immune cells adhension and recruitment." (PMID 39659236, 2024). "Prior study revealed that CCN1 enhanced the migration and invasion of glioma cells dependence on binding to integrins and activating downstream of STAT3 pathway." (PMID 39659236, 2024). "Though the high expression of GPX1 and CCN1 both indicated worse prognosis in glioma, only GPX1 was significantly upregulated in GBM compared with normal brain tissue." (PMID 35910786, 2022). "Coxsackieviruses (CVB) and herpes simplex virus-1 (HSV-1) infection increase CCN1 expression in HeLa cell and rat glioma cells." (PMID 35418961, 2022). "CCN1 levels were elevated both in its secreted form in blood samples and in tumour tissues from glioma patients." (PMID 35052688, 2021). "It has been reported that S1P induces the expression of urokinase plasminogen activator (uPA) and CCN1 (Cyr61) protein which together results in glioma invasion, growth, and angiogenesis." (PMID 33920887, 2021). "In the current study, CCN1 levels were explored in patient-derived glioma tissue and GBM cell lines." (PMID 35052688, 2021). "A total of 147 tumour samples from 80 patients with glioblastoma and 67 patients with lower grade glioma were analysed and we classified cases based on high or low CCN1 expression level." (PMID 28785028, 2017). "To understand the molecular mechanisms that regulate CCN1 expression, we examined 147 tumour samples from 80 patients with glioblastoma and 67 patients with lower grade glioma." (PMID 28785028, 2017). "In lower grade glioma, the CCN1 high expression group tended to have a high frequency of PIK3R1Met326Ile, but it was not statistically significant (astrocytoma, p = 0.2488; oligodendroglioma, p = 0.3158, Fisher’s exact test)." (PMID 28785028, 2017). "Expression of CCN1 has been shown to correlate with tumor progression and poor patient prognosis in glioma patients and to enhance tumorigenicity of glioma cells." (PMID 25309325, 2014). "In glioma cells, CCN1 can enhance tumorigenicity by promoting cell proliferation and survival through integrin αvβ3- and β1-activated ILKs to stimulate the β-catenin T-cell factor (TCF)/lymphocyte-enhancing factor 1 (LEF-1) and PI3K/PKB signaling pathways." (PMID 22481923, 2012). "The elevated expression of CCN1 in tumorigenic glioma cell lines accelerates their growth in vitro and enhances their anchorage-independent proliferation in soft agar." (PMID 22481923, 2012). "Additionally, extracellular CCN1 limited the efficacy of oncolytic treatments in glioma by modulating macrophage activity via interacting with integrin α6β1." (PMID 39659236, 2024). "In addition, through CGGA data analysis, we found that CCN1, 2, 3, and 4 were all enhanced in relapsed glioma." (PMID 36589241, 2022). "To better understand the relevance of our findings on the correlation between CCN1 expression and tumour aggressiveness/grade and concentration in matched patient serum, we next investigated the effects of blocking CCN1 in the established glioma cell lines U251 and U87." (PMID 35052688, 2021). "CCN1 is highly expressed in primary gliomas, as well as in high-grade glioma cell lines." (PMID 35052688, 2021). "Moreover, CCN1 expression levels were concomitant with high-grade tumours, especially in comparison to expression levels in lower-grade gliomas." (PMID 35052688, 2021). "Thus, NF2 controls the invasiveness of glioma through YAP-dependent expression of CYR61/CCN1 and miR-296-3p." (PMID 32676008, 2020). "Overexpression of either CCN1 or PIK3R1Met326Ile promoted glioma cell invasion in vitro." (PMID 28785028, 2017).